H2AX (H2A.X variant histone)
Diseases named in the same sentence as H2AX in open-access papers (continued):
Sharing a sentence is not in itself a finding about the gene and the disease.
cancer (continued). "It was reported that persistent γ-H2AX foci were higher in in vitro X-ray irradiated lymphocytes of children with cancer compared to healthy children, suggesting that cancer-suffering children display impaired DNA repair capacity." (PMID 31546867, 2019). "Similar to other TopIB poisons, indenoisoquinolines arrest cell cycle progression in both S and G2-M phases in human cancer cells, with the phosphorylation of H2AX taking place mainly in S-phase." (PMID 31563118, 2019). "In cancer cells subjected to replicative and oxidative stress, p-H2AX signals are evident in the nucleus in a diffuse and uniform manner." (PMID 31514456, 2019). "Using a novel monoclonal antibody that binds exclusively to the phosphorylated C-terminus of H2AX, we demonstrate that H2AX phosphorylation is systematically pan-nuclear in cancer cells stressed with RS-inducing drugs just before they die." (PMID 30871194, 2019). "Overall, our data indicate that the pan-nuclear γ-H2AX phenotype can be observed in a variety of cancer cells following prolonged intense RS induction." (PMID 30871194, 2019). "In a previous work we have observed a similar nuclear swelling and rise of pan-γ-H2AX pattern in cancer cells transduced with anti-PCNA or anti-DNA polymerase alpha inhibitory Fabs." (PMID 30871194, 2019). "Chronic ROS leads to H2AX poly-ubiquitination due to increased interaction between H2AX and E3 ubiquitin ligase RNF168, which results in reduced level of H2AX and increased sensitivity of cancer cells to chemotherapy." (PMID 29594114, 2018). "In particular, we observed increased phospho-H2AX levels in cancer cells when NDUFA4L2 was silenced, suggesting that NDUFA4L2 plays an important role in ROS control and that its loss generates cell stress." (PMID 30538212, 2018). "We previously found that SUV39H2 methylates histone H2AX at lysine 134, which enhances the accumulation of γ-H2AX and enhances DNA repair activity in human cancer." (PMID 30159125, 2018). "Since NDUFA4L2-silenced cancer cells showed an increased ROS production, and superoxide radicals can induce histone modifications, we analyzed the phosphorylation of the H2AX histone." (PMID 30538212, 2018). "Combination of OTS193320 with doxorubicin (DOX) resulted in reduction of γ-H2AX levels as well as cancer cell viability compared to a single agent OTS193320 or DOX." (PMID 30159125, 2018). "Extensively phosphorylated pan-γ-H2AX chromatin was also seen in cancer cells hit by multiple α-particles in the range of up to several Gy40." (PMID 29396412, 2018). "Our data have shown that SUV39H2 inhibition plays important regulatory roles in γ-H2AX production in cancer cells by these two small-molecular compounds." (PMID 30159125, 2018). "This methylation plays a crucial role in increasing chemo- and radio-resistance in cancer cells through the enhancement of γ-H2AX production by SUV39H2-dependent methylation." (PMID 30159125, 2018). "The genotoxicity of Roy-Bz in human cancer cells was evaluated by checking comet-positive cells and histone H2AX phosphorylation on Serine-139 (γH2AX) as markers of DNA damage (single/double-strand breaks)." (PMID 29348560, 2018). "In additions, the ROS scavenger NAC inhibited TTB-mediated γ-H2AX foci formation and apoptotic cell death in cancer cells." (PMID 28245605, 2017). "Time-dependent H2AX phosphorylation at Ser139 after SSa treatment was observed in these cancer cells." (PMID 29245990, 2017).
cancer (continued). "The numbers of α-SMA-positive cancer-associated fibroblasts (CAFs) (P = 0.049) and α-SMA-positive CAFs co-expressing p21Waf1/Cif1 (P = 0.038), γ-H2AX (P = 0.065), and IL-6 (P = 0.048) were greater for SH-HCCs than C-HCCs." (PMID 28273155, 2017). "Our results highlight the potential of the γ-H2AX ELISA to improve the study of mutagenesis and DNA damage response pathways in cancer." (PMID 28158293, 2017). "To explore this potential, we utilized the γ-H2AX ELISA assay to simultaneously analyze multiple extracts from the NCI-60 cancer cell line panel." (PMID 28158293, 2017). "We examined the potential effects of RIT on proliferation, DNA double-stranded breaks and apoptosis of cancer cells by immunohistochemical staining, which can detect Ki-67-, p-H2AX-, TUNEL-positive cells." (PMID 27246980, 2016). "DNA damage clearance is a significant factor of radioresistance in cancer cells and γ-H2AX has been employed as a sensor of double-strained DNA breaks (DSBs) after γ-irradiation treatment." (PMID 27317767, 2016). "Here, we uncover a new mechanism, by which ROS downregulate H2AX protein levels and sensitize cancer cells to anti‐cancer agents." (PMID 27006338, 2016). "First, using the M21, HT29, HT-1080 and HeLa cell lines, we confirmed that S-phase cell cycle arrest and γ-H2AX foci induction by SFOM-0046 is a general mechanism occurring in diverse cancer cell lines." (PMID 27001483, 2016). "Collectively, our data suggest that reduced antioxidant defences and subsequent decrease in total H2AX protein enhance sensitivity to DNA‐damaging anti‐cancer agents that is critical for TNBC patient survival." (PMID 27006338, 2016). "Several previous studies have nicely demonstrated that reduced amount of H2AX increases DNA damage and sensitivity to anti‐cancer therapies." (PMID 27006338, 2016). "In some cells not in S phase with 0 Gy treatment, large numbers of endogenous γ-H2AX foci were observed in all of the canine cancer cells." (PMID 27257868, 2016). "In human cancer cell lines, the relationship of residual levels of γ-H2AX or rates of its disappearance to clonogenic cell survival in cancer cells has been studied by several investigators, and correlations were found in some studies, but not all." (PMID 27257868, 2016). "In recent years, the γ-H2AX biomarker has become a powerful tool to monitor DNA DSBs in translational cancer research studies." (PMID 26618801, 2015). "We also observed a significant reduction in γ-H2AX levels when comparing primary and residual cancers." (PMID 26544894, 2015). "In some instances, the identified genes have already been shown a potential value for assessing response to cancer treatment, such as neuroblast differentiation-associated protein (AHNAK) and H2A histone family, member X (H2AX)." (PMID 26089344, 2015). "As expected, H2AX genes were also significantly highly expressed after the plasma treatment, by 2.6 to 5.7 fold (p < 0.05) in both cancer cells." (PMID 25715710, 2015). "In a further study of the possible mechanism underlying plasma-induced cancer cell apoptosis at 24 h, we determined the mRNA gene expressions of Bcl-2, BAX, BAK1 and H2AX by real time quantitative PCR analysis." (PMID 25715710, 2015). "The endogenous level of γ-H2AX was highly expressed in many premalignant lesions, cancer cells and solid tumors." (PMID 25537504, 2015). "The increase in CDKN1A and γ-H2AX expression in D384 cells upon DhL exposure also indicated cell cycle arrest and DNA damage response of cancer cells, in which DhL would induce DNA repair mechanisms." (PMID 26309132, 2015). "In summary, attenuation of H2AX K134 methylation appears to enhance both radio- and chemosensitivity of cancer cells." (PMID 25487737, 2014). "Overall, our results suggest that H2AX methylation plays a role in the regulation of γ-H2AX abundance in cancer." (PMID 25487737, 2014).
cancer (continued). "As previously observed with HDAC inhibitor treatment, shRNA-mediated depletion of HDAC3 caused a significant (approximately 4-fold) up-regulation of the DNA damage marker γ-H2AX in cancer cells." (PMID 25026298, 2014). "Based on H2AX function in DNA repair and in maintaining DNA stability, the use of H2AX / γH2AX as marker for early cancer detection, prognosis and therapeutics has been proposed." (PMID 25003966, 2014). "The phosphorylated histone H2AX (γH2AX) recruits DNA damage repair enzymes, and it can be used as a marker of active DNA damage signaling in translational cancer research." (PMID 24858818, 2014). "In order to elucidate the observed increase in the mean numbers of γ-H2AX foci in cells derived from hypersensitive cancer patients, we further analyzed the distributions of γ-H2AX foci within different cell samples." (PMID 23617930, 2013). "Our Western blot analyses showed the increase of DNA damage marker γ-H2AX in cancer cells after Ching001 treatment, which was confirmed by immunofluorescence for γ-H2AX." (PMID 23646116, 2013). "Most studies of γ-H2AX staining report a rapid (within hours) appearance of foci in cancer cell lines in cell culture." (PMID 23112954, 2012). "γ-H2AX levels are elevated in cancer and aging cells in which it marks both DSBs and abnormal telomeres." (PMID 21325706, 2011). "In line with current knowledge that PARP inhibition induces DSBs in cancer cells, we show that the PARPi does so also in hESCs and NPs leading to increased γ-H2AX foci formation." (PMID 20844317, 2010). "Our findings encourage further studies to explore H2AX and the cellular pathways that control its expression as anti-cancer drug targets." (PMID 18616816, 2008). "Our findings encourage further studies to exploit H2AX and the cellular mechanisms that regulate its expression levels as novel anti-cancer drug targets." (PMID 18616816, 2008). "Our results indicated a dose-dependent increase in γ-H2AX fluorescence intensity by curcumin in the cancer cells, but not in non-malignant ovarian epithelial cells, indicating that curcumin exerts its cytotoxic effect more preferably in cancer cells." (PMID 40163489, 2025). "In this study, γ‐H2AX expression was found to increase with cancer severity in BOSCC tissue." (PMID 40569274, 2025). "Moreover, arsenic-exposed cells displayed persistent DNA damage, as indicated by increased γ-H2AX foci, accompanied by nuclear structural alterations and elevated expression of cancer stem cell markers, including OCT2, CD133, and ALDH1." (PMID 40368219, 2025). "The relationship between H2AX expression and microsatellite instability, a carcinogenic mechanism driven by mismatch repair defects, further emphasizes the connection between γH2AX and cancer progression." (PMID 40141048, 2025). "This is consistent with our previous studies in which pretreatment with pemetrexed, a nucleotide synthesis inhibitor, further augmented chemo- and radiotherapy-induced H2AX phosphorylation, resulting in increased anti-cancer efficiency of the combination regimens." (PMID 40158058, 2025). "Furthermore, SPC-A1-miRNAs − 410 cancer cells are much more radioresistant, evidenced by a shorter proliferation delay and lower amounts of -H2AX." (PMID 38965615, 2024). "As reported in the literature, the quantification of γH2AX levels relative to total H2AX expression could provide a normalized value representative of the amount of DNA damage in cancer cells." (PMID 38675528, 2024).
cancer (continued). "Therefore, we digest the millimeter-sized gel to recover the cancer cells and analyze their response to radiation via r-H2AX and 7AAD level instead." (PMID 39334323, 2024). "We examined the DNA damage repair response by analyzing γ-H2AX level in cancer cells." (PMID 38709242, 2024). "Histone H2AX is critical in the regulation of DNA damage, which in turn may be a mediator of increased apoptosis in several cancer types as a result of pharmacological PARP inhibition with and without chemotherapy." (PMID 36768904, 2023). "Furthermore, accumulating evidence shows the ubiquitination of H2AX serves vital roles in cancer and DNA damage." (PMID 37870748, 2023). "To determine whether increased radioiodine sensitivity of cancer cells expressing oNIS or oNIS+BRD was associated with defective DSB repair, we measured the level of DNA DSBs by counting the number of γ-H2AX foci generated after damage." (PMID 36769088, 2023). "Furthermore, β-radiation has been observed to enhance the formation of γ-H2AX and 53BP1 nuclear foci in various cancers." (PMID 38140100, 2023). "ARN3261 induced higher levels of γ-H2AX in cancer cells than normal cells." (PMID 35642638, 2022). "PC3 cells, like many other cancer cell lines, have quite a high background of γ-H2AX foci." (PMID 35852717, 2022). "Injection of irradiated dying cancer cells pre-labelled with BrdU intravenously into mice led to uptake and genomic integration of BrdU labelled cfCh particles into nuclei of vital organs accompanied by activation of H2AX." (PMID 33597956, 2021). "Moreover, this nanobody and the transduction strategy described will likely pave the way to reliably study the dynamics of γ-H2AX in individual cancer cells under a variety of conditions and in response to genotoxic stimuli in particular." (PMID 34282773, 2021). "Notably, immunofluorescence staining of the histone protein and key molecular marker of DNA damage, γ-H2AX, showed that co-treatment of irradiated cancer cells with esomeprazole significantly enhanced accumulation of phosphorylated H2AX foci in the nuclei." (PMID 34262645, 2021). "Indeed, H2AX phosphorylation during the EMT in cancer cell line models has previously been shown to play a role in transcriptional regulation of the vast gene expression changes that occur." (PMID 32888504, 2020). "Furthermore, H2AX phosphorylation (γ-H2AX) was found to inhibit histone methylation via the binding to PRMT1 in cancer patients with overexpression of protein phosphatase 2A (PP2Ac), thereby increasing the level of histone phosphorylation." (PMID 33193750, 2020). "γ-H2AX is studied by many research’s teams in the context of cancer treatment." (PMID 31313023, 2019). "Curcumin-mediated overexpression of H2AX, a prominent marker of DNA strands break, reveals its apoptosis induction potential and thus suggest anti-proliferative and suppressive growth feature which is imperative for cancer treatment." (PMID 30333956, 2018). "Second, despite the 80+% suppression of X-ray-induced γ-H2AX foci and other DNA damage markers by PrC-210, the PrC-210 effect upon suppression of X-ray-induced cancer is currently unknown." (PMID 30135082, 2018).
cancer (continued). "Overall, the γ-H2AX ELISA represents a novel approach to quantifying DNA damage, which may lead to a better understanding of mutagenic pathways in cancer and provide a useful biomarker for monitoring the effectiveness of DNA-damaging anticancer agents." (PMID 28158293, 2017). "The γ-H2AX ELISA assay represents a useful tool that could improve the clinical study of these drugs and their effects on cancer cells." (PMID 28158293, 2017). "Co-incubation with a Chk1 inhibitor achieves synergistic apoptosis in cancer cells, with a significant increase in phospho(Ser139) histone H2AX (γ-H2AX) levels and foci indicating increased conversion of stalled replication forks to double-strand breaks (DSBs)." (PMID 27558808, 2016). "This discrepancy might be due to the high endogenous γ-H2AX foci in cancer cells relative to normal cells as previously observed, which was also observed in canine cancer cells." (PMID 27257868, 2016). "To examine whether the response of cells to DNA DSBs correlates with radiosensitivity in the canine cancer cell lines, we used γ-H2AX assay in the five most radioresistant and five most radiosensitive cell lines selected from SF2 ranking." (PMID 27257868, 2016). "Relating hypomethylation to cancer in the context of the H2AX promoter may complement previous observations linking H2AX overexpression and fibroblast immortality, and position H2AX overexpression as a putative contributor to STAT5-induced carcinogenesis." (PMID 27260000, 2016). "In addition, H2AX mRNA gene expression levels were also increased after plasma treatment in cancer cells." (PMID 25715710, 2015). "Detection of γ-H2AX foci has been used as a biomarker for aging and cancer, as a biodosimeter for drug development and radiation exposure, as well as for clinical trials for cancer chemo- and radiotherapy." (PMID 24527431, 2014). "Similar to cancer cells in which HDAC3 was depleted by shRNA, Hdac3-deficient MEFs also exhibited decreased expression levels of BRCA1 and ATR but increased levels of CHK1 and γ-H2AX." (PMID 25026298, 2014). "Furthermore, introduction of K134-substituted histone H2AX enhanced radio- and chemosensitivity of cancer cells." (PMID 25487737, 2014). "To determine whether MSH3 is involved in DNA DSB repair, we determined the effect of anti-cancer drug treatment upon expression of the DSBs markers, phosphorylated histone H2AX (pH2AX) and Checkpoint kinase 2 (pChk2)." (PMID 23724141, 2013). "This phenomenon may be due to H2AFX promoter variants having opposing effects in different cell types, or differing roles for H2AX in development of these cancers." (PMID 24069324, 2013). "The lack of association of γ-H2AX foci with cancer was somewhat surprising given that cancer cells have been found to have increased endogenous γ-H2AX levels compared to normal cells." (PMID 23029205, 2012). "Therefore, it is highly questionable if the phosphorylation of H2AX is suitable to detect the slight differences in radiosensitivity among individual cancer patients." (PMID 23110060, 2012). "Of the 908 carcinomas, 440/908 (48.5%) had nuclear γ-H2AX expression." (PMID 23154512, 2012). "The lymphocytes present in peripheral blood have been utilized to detect γ -H2AX formation during cancer treatment, but these terminally differentiated cells may respond poorly to anticancer drugs that interfere with DNA metabolism." (PMID 21325706, 2011).